CRY1 (cryptochrome circadian regulator 1)
Diseases named in the same sentence as CRY1 in open-access papers (continued):
Sharing a sentence is not in itself a finding about the gene and the disease.
melanoma (6 papers, 2016 to 2024). A malignant, usually aggressive tumor composed of atypical, neoplastic melanocytes. "It was found that Per1, Per2, Clock, and Cry1 expression was reduced in the melanoma biopsies as compared to adjacent normal skin in the majority of melanoma patients." (PMID 27128901, 2016). "Furthermore, Cry1 gene expression is severely downregulated while melanogenesis ability is significantly enhanced in B16 melanoma cells in comparison with normal melanocytes, suggesting that CRY1 may be involved in melanin deposition." (PMID 36814484, 2023). "By comparing biopsies from human melanoma to non-tumorous samples, they were able to show that the expression of Per1, Per2, Clock and Cry1 clock genes and corresponding protein levels in the nucleus were reduced by 30%–60% in melanoma versus normal skin." (PMID 27231897, 2016).
mood disorder (6 papers, 2010 to 2023). A cognitive disorder a disturbance in which the person's mood is hypothesized to be the main underlying feature. "Genetics studies have found associations with CLOCK, PER1-3, and CRY1, and Sirtuin genes in mood disorders." (PMID 21542937, 2011).
type 2 diabetes (6 papers, 2012 to 2025). "In contrast, type 2 diabetes was associated with rs12315175, close to the CRY1 gene, and rs2292912, located in the CRY2 gene, although statistical significance was nominal in both cases." (PMID 22485135, 2012). "In conclusion our study has confirmed the association between type 2 diabetes and variants of the CRY2 gene and suggested a potential role for the CRY1 gene in disease development." (PMID 22485135, 2012). "Our data demonstrate a dysregulation of the molecular clock system in PBMCs from participants with type 2 diabetes, manifested by a decrease in CLOCK, CRY1, p-BMAL1 and PER2 protein levels and an increase in BMAL1 and NR1D1 mRNA levels." (PMID 38981930, 2024). "Impairment of the circadian clock genes such as CLOCK, BMAL1, cryptochrome (CRY1 and CRY2), and period (PER1, PER2, and PER3) contributes to the decrease in glucose tolerance, defective β-cell function, and the development of type 2 diabetes." (PMID 28352282, 2017). "Participants with type 2 diabetes showed increased BMAL1 and NR1D1 mRNA levels and decreased protein levels of circadian locomotor output cycles kaput (CLOCK), cryptochrome 1 (CRY1), phosphorylated basic helix-loop-helix ARNT like 1 (p-BMAL1) and period circadian protein homologue 2 (PER2)." (PMID 38981930, 2024).
Hyperglycemia (5 papers, 2012 to 2023). An increased concentration of glucose in the blood. "Mutational analyses have identified two distinct light chain 3 (LC3)-interacting region (LIR) motifs on CRY1 that regulate CRY1 degradation, providing potential targets for controlling hyperglycemia." (PMID 37626963, 2023). "Although SREBP1c fails to upregulate CRY1 expression in db/db mice, overexpression of CRY1 attenuates hyperglycaemia through reduction of hepatic FOXO1 protein and gluconeogenic gene expression." (PMID 27412556, 2016).
Chronic Lymphocytic Leukemia (4 papers, 2012 to 2021). "In chronic lymphocytic leukemia, the ratio of PER2 to CRY1 is suggested to be a prognostic marker that predicts survival outcomes of patients, with a low PER2:CRY1 having the best outcomes." (PMID 33089179, 2019). "Cryptochrome 1 (CRY1) is a core component of the mammalian circadian clock and we have previously shown its deregulated expression in a subgroup of patients with chronic lymphocytic leukemia (CLL)." (PMID 22470559, 2012).
colon cancer (4 papers, 2013 to 2024). "Recently, a study reported a sex-dependent association between circadian genes and prognosis of colon cancer patients, and women with high tumor Cry1 expression had a worse outcome." (PMID 38245882, 2024). "Overall, the phenotypic differences among the colon cancer cell lines investigated may underlie diverse CRY1 and CRY2 expression patterns and a related genetic landscape that could influence cell survival and response to chemotherapy." (PMID 26768731, 2016). "One study found that Cry1 and other circadian gene (Cry2, Per2 and BamlI) mRNA expression levels were similar in colon cancer and adjacent normal mucosa." (PMID 23626715, 2013). "Altered CRY1 and CRY2 expression patterns and the interplay with the genetic landscape in colon cancer cells may underlie phenotypic divergence that could influence disease behavior as well as CRC patients survival and response to chemotherapy." (PMID 26768731, 2016). "The different CRY1 and CRY2 expression levels and time related profiles plus the different apoptotic, proliferative and cytotoxic responses observed in vitro in the studied colon cancer cell lines could be related to the dissimilarity in their chromosomal abnormalities and genetic background." (PMID 26768731, 2016).
Glucose intolerance (4 papers, 2017 to 2023). Glucose intolerance (GI) can be defined as dysglycemia that comprises both prediabetes and diabetes. "Genetic loss of CRY1/CRY2 results in decreased glucose intolerance, increased glucose level, and constitutively high levels of circulating corticosterone in mice." (PMID 28352282, 2017). "In mice, the loss of Cry1 and/or Cry2 resulted in glucose intolerance and constitutively high levels of circulating corticosterone, suggesting reduced suppression of the hypothalamic-pituitary-adrenal (HPA) axis coupled with increased glucocorticoid transactivation in the liver." (PMID 32437460, 2020).
leukemia (4 papers, 2022 to 2023). A malignant (clonal) hematologic disorder, involving hematopoietic stem cells and characterized by the presence of primitive or atypical myeloid or lymphoid cells in the bone marrow and the blood. "In medical research targeting clock genes, CRY1 may be related to the development of bladder cancer and leukemia, and therapeutic agents selective for CRY2 have been reported to be effective in treating glioblastoma, a malignant brain tumor." (PMID 37056311, 2023). "Furthermore, it is possible that the deregulation of CRY1 expression, either high or low, could lead to leukemia progression through different mechanisms, but more studies are required to verify the action of this gene in the cell cycle." (PMID 35897788, 2022). "Although CRY1 and CRY2 were down-regulated in most of the identified results in leukemia patients, some cases showed a high expression of these genes." (PMID 35897788, 2022).
lung carcinoma (4 papers, 2014 to 2022). "Previous studies showed that circadian rhythm-related factors such as the ARNTL, CLOCK, RORA, RORB, CRY1, CRY2, and PER3 genes were associated with a higher risk of lung cancer." (PMID 36385012, 2022). "According to our genome-wide transcriptomic analysis and Q-PCR validation, we found that the DNA damage-related genes ERCC1, XPC, and CRY1 were up-regulated in hinokitiol-treated lung cancer cells." (PMID 25105411, 2014). "Furthermore, we used the CCLE to analyze mRNA expression levels of PER1, PER2, PER3, CRY1, and CRY2 in lung cancer cell lines in current lung cancer research." (PMID 36385012, 2022).
lymph node metastasis (4 papers, 2013 to 2020). "The combined ORs were 0.89 (95%CI: 0.47∼1.68, Ρ=0.722) forCry1 and differentiation, 0.86 (95%CI: 0.22∼3.26, Ρ=0.825) for Cry1 and invasion depth and 0.55 (95%CI: 0.29∼1.03, Ρ=0.062) for Cry1 and lymph node metastasis." (PMID 32437452, 2020). "Clinical pathological analysis showed that Cry1 expression was significantly correlated with lymph node metastasis (p = 0.004) and the TNM stage (p = 0.003)." (PMID 23626715, 2013). "Higher TNM stage and the presence of lymph node metastasis were significantly correlated with higher levels of Cry1 expression, suggesting that Cry1 can be used as a marker to determine the progression of CRC." (PMID 23626715, 2013). "Higher CRY1 expression was found in patients with lymph node metastasis and more advanced stages." (PMID 24708606, 2014).
schizophrenia (4 papers, 2018 to 2025). A major psychotic disorder characterized by abnormalities in the perception or expression of reality. "Circadian alterations in expression levels of CLOCK, CRY1, and PER2 mRNA were found in schizophrenia." (PMID 29534090, 2018). "In individuals with first-episode schizophrenia, the mRNA expression of CLOCK, PER2, and CRY1 genes significantly decreases in the early stages, suggesting that the circadian rhythm disturbance may be part of the pathological process of schizophrenia rather than a result of long-term drug treatment." (PMID 40243466, 2025).
Sepsis (4 papers, 2017 to 2025). Sepsis is defined as life-threatening organ dysfunction caused by a dysregulated host response to infection. "The increased levels of cry1 in IL-6 KO are paralleling observations in plasma levels of sepsis patients were an increase in IL-6 was associated with a decrease in cry1 mRNA." (PMID 28382017, 2017). "In a study on circadian rhythms in patients with sepsis, it was suggested that sepsis suppresses the expression of the Circadian gene, such as CRY1, REV-ERBα, NR1D2, DBP, and PER2." (PMID 39097582, 2024). "As clock genes, PER2, PER3, and CRY1 may be markers of sepsis severity." (PMID 40362233, 2025).
sleep disorder (4 papers, 2020 to 2024). A change from the patient's baseline sleeping pattern, in the hours slept and/or an alteration/dysfunction in the stages of sleep. "Disruption or mutations in the CRY1 gene can alter circadian rhythms and lead to sleep disorders and metabolic dysregulation." (PMID 39728504, 2024). "We also found in the bibliography that Harryflintia was positively associated with a circadian clock gene (Cry1) whose mutations were related to sleep disorders." (PMID 33808770, 2021). "Thus, Cry1 knockout or Cry2 knockout mice are good models for studying the underlying mechanisms of circadian sleep disorders in humans." (PMID 39728504, 2024).
Stroke (4 papers, 2020 to 2026). Sudden impairment of blood flow to a part of the brain due to occlusion or rupture of an artery to the brain. "The present investigation illustrated that expression levels of genes implicated in circadian rhythms (such as BMAL1 and CRY1) are lower in patients with nighttime strokes." (PMID 41503592, 2026). "In our study, the observed increases in Per1 and Cry1 expression suggest that these genes may play a key role in mediating the circadian disturbances seen after stroke." (PMID 39957482, 2025). "Moreover, coordinated changes in the co-expression of PER1 and CRY1 suggest that the core clock gene network plays a critical role in post-stroke sleep homeostasis disruption." (PMID 41451215, 2025).
cervical cancer (3 papers, 2022 to 2025). A primary or metastatic malignant neoplasm involving the cervix. "On the other hand, high levels of CRY1 expression were found in gastric and cervical cancer, and were associated with a poor prognosis." (PMID 35897788, 2022). "In cervical cancer, Cry1 regulates chemoresistance by inhibiting apoptosis through the STAT3 pathway." (PMID 41142939, 2025). "Additionally, Cry1 modulates chemoresistance in coordination with NANOG in cervical cancer patients." (PMID 41142939, 2025).
colitis (3 papers, 2021 to 2023). Inflammation of the colon. "On the contrary, we found that in colorectal stromal cells, colitis was associated with decreases in the mRNA levels of Arntl, Clock, Cry1, Cry2, Per2, Per3, Nr1d1, Npas2, and BBR restored the expression of these genes except Per2." (PMID 36528592, 2022). "Examination of C57BL/6 mice with DSS-induced colitis revealed significantly reduced Cry1, Per2, Npas2 and Rev-erbα expression, but significantly increased expression of Rorα." (PMID 37218867, 2023). "We also compared the expression of several key circadian genes including Arntl, Clock, Cry1, Cry2, Per1, Per2, Per3, Nr1d1, and Npas2 in colon samples collected at 03, 09, 15, and 21 of normal mice, colitis mice, normal mice receiving BBR, and colitis mice receiving BBR." (PMID 36528592, 2022).
epilepsy (3 papers, 2015 to 2023). A brain disorder characterized by episodes of abnormally increased neuronal discharge resulting in transient episodes of sensory or motor neurological dysfunction, or psychic dysfunction. "The rats with absence epilepsy (ie, GAERS) showed diurnal dysregulation of all core circadian clock genes, Per1, Cry1, Clock, and Bmal1, when compared to NECs, or had an epilepsy by time interaction where groups significantly varied depending on the time of day." (PMID 37805809, 2023). "Mutations in PER2 and CRY1 result in advanced phase sleep disorder and delayed phase sleep disorder, respectively; however, neither of these phenotypes includes epilepsy." (PMID 32714261, 2020). "Core clock genes including CLOCK, BMAL1, FBXL21, PER1, PER3, CRY1, and NR1D1 do not show evidence of harboring mutations that cause epilepsy in humans." (PMID 32714261, 2020). "Finally, we showed that temporal differences of sampling can change experimental results for Per1, Per3, Bmal1, Cry1 and Cry2, but not for Clock, which was consistently decreased in rats with epilepsy in all comparison to the naive group." (PMID 26473354, 2015).
insomnia (3 papers, 2021 to 2024). A sleep disorder characterized by difficulty in falling asleep and/or remaining asleep. "Polymorphisms in clock genes have also been associated with MDD including Cry1 and Npas2 and a Clock gene polymorphism was associated with insomnia and relapse in people with MDD." (PMID 36161151, 2022). "In healthy controls, insomnia severity correlated with evening expression of BMAL1, PER1, and CRY1." (PMID 39201748, 2024).
obstructive sleep apnea (3 papers, 2018 to 2023). "In a separate study involving individuals with obstructive sleep apnea (OSA), it was noted that the transcription of BMAL1, CLOCK, and CRY2 was irregular, and the levels of CRY1 and PER3 significantly decreased at midnight." (PMID 38067152, 2023). "Similarly, the combined downregulation in the expressions of CRY1 and PER3 at midnight predicted the severity of the disease in patients with obstructive sleep apnea/hypopnea syndrome." (PMID 32823749, 2020).
steatosis (3 papers, 2021 to 2025). Increased lipid within the cytoplasm of cells. "In contrast to the transcript levels, CLOCK and CRY1 protein levels were lower under steatosis conditions compared to fructose treatment (p = 0.01, p = 0.005, respectively, Student’s t-test), suggesting a direct effect of the fatty acid mixture regardless of the monosaccharide." (PMID 36837757, 2023). "However, supplementation of the mixture with 0.06% Vitamin C and 0.05% niacinamide alleviated steatosis and inflammation in liver of growing-finishing pigs fed diets containing 10% glycerol by reducing the numbers of harmful microbiota and increasing the expressions of CRY1 and SLC7A11." (PMID 40607347, 2025).
Abdominal obesity (2 papers, 2022). Excessive fat around the stomach and abdomen. "In the female VLFC, the major homozygous allele of CLOCK rs11932595 and CRY1 rs3741892 had a higher abdominal obesity risk than those in the OFC." (PMID 35276838, 2022).
advanced sleep phase syndrome (2 papers, 2017 to 2020). A very rare circadian rhythm sleep disorder characterized by very early sleep onset and offset possibly resulting in emotional and physical disruptions. "In addition, mutations in PER2 have been linked with advanced sleep phase syndrome, while mutations in CSNK1D and CRY1 have been linked to delayed sleep phase syndrome." (PMID 29230328, 2017).
anxiety disorder (2 papers, 2013 to 2025). A category of psychiatric disorders which are characterized by anxious feelings or fear often accompanied by physical symptoms associated with anxiety. "The aim of the current paper is to study the associations of CRY1, CRY2 and TTC1 genes in depressive and anxiety disorders." (PMID 23951166, 2013). "Our objective was to study two core circadian clock genes, CRY1 and CRY2 as well as TTC1 that interacts with CRY2, in relation to depressive and anxiety disorders." (PMID 23951166, 2013).
bladder cancer (2 papers, 2021 to 2023).
chronic kidney disease (2 papers, 2018 to 2023). Impairment of the renal function secondary to chronic kidney damage persisting for three or more months. "Liu found that miR-181a can inhibit the activation of TLR/NF-KB signal pathway by down-regulating the level of target gene CRY1, delay the progression of glomerulosclerosis and tubular epithelial injury in chronic kidney disease, reduce the degree of renal injury and promote renal homeostasis." (PMID 37565908, 2023). "Upregulation of miR-181a can down-regulate the expression of CRY1 protein and promote the excretion of CRY1 by inhibiting NF-kB signal pathway, thus alleviating glomerulosclerosis and tubular epithelial injury in rats with chronic kidney disease." (PMID 37565908, 2023).
chronic myeloid leukemia (2 papers, 2015 to 2019). "Decreased expression of PER1/2/3 (and CRY1/2 and BMAL1) has also been observed in the blood of patients with chronic myeloid leukemia (CML) when compared to the blood of healthy individuals." (PMID 33089179, 2019). "It has been demonstrated that the expression levels of the human CRY1, CRY2, PER1, PER2, PER3, and BMAL1 genes were down-regulated in both the chronic phase and blast crisis in chronic myeloid leukemia (CML)." (PMID 26253128, 2015).
Cluster headache (2 papers, 2021 to 2025). A type of headache characterized by repeated attacks of unilateral pain lasting 15 to 180 minutes and associated with local autonomic signs. "They found that the variant rs8192440 in the CRY1 gene was associated with cluster headache and the major allele G was more common in cluster headache patients than in controls." (PMID 39560176, 2025). "The exonic CRY1 variant rs8192440 was associated with cluster headache on allelic level (p=0.02) and this association was even more pronounced in a subgroup of patients with reported diurnal rhythmicity of attacks (p=0.002)." (PMID 34256648, 2021). "We discovered a disease-associated variant in the CRY1 gene and slightly increased CRY1 gene expression in tissue from cluster headache patients, strengthening the hypothesis of circadian dysregulation in cluster headache." (PMID 34256648, 2021). "In this case-control study, we investigated the role of cryptochrome (CRY) genes in cluster headache by screening 628 cluster headache patients and 681 controls from Sweden for four known genetic variants in the CRY1 (rs2287161 and rs8192440) and CRY2 (rs10838524 and rs1554338) genes." (PMID 34256648, 2021). "Lithium,indicated as a prophylactic treatment for cluster headache has been found to significantly increase the expression of Per2 and Cry1, and reduce the expression of Per3, Cry2, and Bmal1." (PMID 39560176, 2025). "We found a small significant difference in CRY1 gene expression between cluster headache patients and control individuals (p=0.04), but we could not identify an effect of the associated variant rs8192440 on CRY1 expression." (PMID 34256648, 2021). "One Swedish case-control study investigated the role of four SNPs within CRY1 and CRY2 genes in cluster headache; they selected rs2287161, rs8192440, rs10838524, and rs1554338 SNPs according to previous associations between them and several neurological and psychiatric disorders." (PMID 39560176, 2025).